GIPR (gastric inhibitory polypeptide receptor)
Diseases named in the same sentence as GIPR in open-access papers (continued):
Sharing a sentence is not in itself a finding about the gene and the disease.
Obesity (continued). "Several of the high-scoring genes (score ≥ 11) are known to be implicated in obesity (such as DGKI [score: 22.8], MC4R [19.6], BDNF [19.6], MTOR [16.8], SH2B1 [14.8], GIPR [14.3], AKT3 [11.6], and LEPR [11.6])." (PMID 38754426, 2024). "A GIPR knockout in either the whole body or selectively in inhibitory GABAergic neurons protects against diet-induced obesity, whereas a knockout in excitatory glutamatergic neurons had a negligible effect." (PMID 39612941, 2024). "The apparent synergy between GLP-1R mimetics and GIPR antagonists has been exploited elsewhere in the pursuit of GIP MABs for obesity management." (PMID 38861364, 2024). "As such, it has been demonstrated that GIPR-null mice are protected against high-fat-fed-induced obesity and insulin resistance, indicating a role for the GIPR in the onset of obesity." (PMID 38861364, 2024). "While most studies have assessed GIPR antagonism in rodent models, more work is needed to further elucidate the impact of GIPR antagonists in patients with T2D and obesity." (PMID 38579777, 2024). "Delineating the spatial contribution of GIPR cells for the anti-obesity effects of acyl-GIP is key for a better understanding of this important new class of drugs." (PMID 38492844, 2024). "That said, as with GIPR agonism, it is clear that the metabolic advantages of sustained GIPR antagonism in obesity and obesity-driven forms of diabetes can be enhanced by concurrent GLP-1 receptor (GLP-1R) activation." (PMID 38861364, 2024). "The global GIPR KO (GIPRKO) was protective against HFD-induced obesity as has been previously reported." (PMID 39612941, 2024). "The anti-obesity effects of GIPR antagonism antibody, both alone and in combination with GLP-1RAs, have been demonstrated in preclinical models of mice and monkeys." (PMID 39114288, 2024). "In a genetic preclinical study, embryonic GIPR knockout mice fed a high-fat diet were protected from obesity, supporting the role of GIPR antagonism as a method to promote weight loss and prevent weight gain." (PMID 39114288, 2024). "Taken together, there is little doubt that interesting times lie ahead for GIPR agonism and antagonism, either alone or when combined with GLP-1R agonists, as a therapeutic intervention for the management of obesity and associated metabolic disease." (PMID 38861364, 2024). "The therapeutic spectrum of T2D and obesity therapy has recently been enriched by hybrid peptides acting as triple GLP-1R/GIPR/GCGR agonists that target both incretin and glucagon signalling to synergistically elicit favourable metabolic effects." (PMID 37378828, 2023). "There is considerable interest in the pharmacological modification of GIPR signaling as treatment for type 2 diabetes and obesity." (PMID 37250804, 2023). "In particular, a defective GIP/GIPR signalling has been observed in the subcutaneous WAT of individuals with obesity and insulin resistance." (PMID 37378828, 2023). "ADRβ3 and GIPR are thought to provide great therapeutic opportunities in obesity and type 2 diabetes." (PMID 36766718, 2023). "As insulin resistance and obesity are strong risk factors for nonalcoholic fatty liver disease (NAFLD), in the current study we investigated the effects of combined GIPR/GLP1R agonism on NAFLD development." (PMID 37379656, 2023). "The development of single-molecule co-agonists for the glucagon-like peptide-1 (GLP-1) receptor (GLP-1R) and glucose-dependent insulinotropic polypeptide (GIP) receptor (GIPR) is considered a breakthrough in the treatment of obesity and type 2 diabetes." (PMID 37946085, 2023). "The incretin receptors, glucagon-like peptide-1 receptor (GLP-1R) and glucose-dependent insulinotropic polypeptide receptor (GIPR), are prime therapeutic targets for the treatment of type 2 diabetes (T2D) and obesity." (PMID 36774542, 2023).
Obesity (continued). "The genetic or pharmacological blockade of GIPR attenuates obesity development in rodents, whereas GIP overexpression reduces diet-induced obesity and improves glucose metabolism." (PMID 36834794, 2023). "GIPR (Gastric Inhibitory Polypeptide Receptor, OMIM * 137241) is one of the genes, which have been identified to be related to obesity risk in various populations." (PMID 36140702, 2022). "The observation that global loss of Gipr protects from diet-induced obesity and that GIP can promote adipocyte lipid storage has inspired the development of GIPR antagonists for the treatment of obesity." (PMID 35299971, 2022). "Nonetheless, as discussed in the preceding subsection, the use of GIPR agonists for the treatment of obesity and T2D is controversial." (PMID 34815532, 2022). "Engagement of GIPR agonism for the treatment of obesity and T2D is regarded with notable scepticism, as the insulinotropic effect of GIP is diminished in patients with T2D179." (PMID 34815532, 2022). "GIPR agonism alone has been shown to reduce bodyweight in mice with obesity, as observed with GIPR agonists with a longer half‐life than endogenous GIP." (PMID 34713962, 2022). "Delineating the relative contribution of GcgR agonism to the efficacy of triple GLP-1R/GIPR/GcgR agonists remains a critical question in the field of obesity pharmacology." (PMID 35809773, 2022). "The research showed that GIPR knockout mice are prevented from developing obesity induced by a high-fat diet (HFD)." (PMID 36140702, 2022). "Other data consistent with our observations support the anti-obesity effects of GIPR antagonists, at least in mice." (PMID 35017517, 2022). "The GIPR is expressed in human adipose tissues, and high levels of circulating GIP are associated with high body mass index (BMI), further supported by a GIPR knock-out mouse model, which is resistant to high fat diet-induced obesity." (PMID 35846282, 2022). "Many genetic and experimental studies pointed to the GIPR-signaling antagonism as a logical therapeutic strategy against diet-induced obesity." (PMID 36145148, 2022). "In the epiWAT from mice with obesity, GIP plays an important role in restraining the production of S100A8/A9 in ATMs, and the deficiency in GIPR in myeloid cells augments myelopoiesis and accumulation of S100A8/A9+ neutrophils and ATMs in the epiWAT." (PMID 33717200, 2021). "The observation that CNS-Gipr KO mice are protected from diet-induced obesity is consistent with the phenotype seen in global germline Gipr KO mice and suggests that central GIPR signaling plays a relevant role in regulating energy metabolism." (PMID 33571454, 2021). "Mice with GIP receptor (GIPR) depletion are protected from diet-induced obesity, and patients with type 2 diabetes show an impaired insulinotropic response to GIP infusion." (PMID 33556643, 2021). "This confusion stems from experimental evidence demonstrating that both GIPR agonists and antagonists improve body weight and glucose control in animal models of obesity." (PMID 33571454, 2021). "While GLP-1/GIP dual-agonists have advanced to phase 3 clinical trials for treating obesity and diabetes, the contribution of GIPR agonism to these applications is questionable." (PMID 33556643, 2021). "It is also worth noticing that the most prominent anti-obesity effect of GIPR agonists as well as antagonist is accomplished in combination with GLP-1R agonists indicating an important interplay between the two incretin hormones and their receptors." (PMID 34760890, 2021). "Surprisingly, antagonizing the GIPR protected against body weight gain in mice with diet-induced obesity and led to a reduced food intake and resting expiratory exchange rate." (PMID 31443356, 2019). "Pro3GIP, initially reported to be a GIPR antagonist, was shown to be protective against diabetes and obesity in rodent models." (PMID 31330984, 2019).
Obesity (continued). "Ambiguity regarding the role of glucose-dependent insulinotropic polypeptide (GIP) in obesity arises from conflicting reports asserting that both GIP receptor (GIPR) agonism and antagonism are effective strategies for inhibiting weight gain." (PMID 31447324, 2019). "Interest in GIPR antagonists developed after studies where GIPR knockout mice were shown to be resistant to diet-induced obesity." (PMID 31330984, 2019). "Dual agonism of GLP-1R/GCGR and very recently triagonism with GLP-1R/GIPR/GCGR have been found to have potent effects to reverse obesity in rodents." (PMID 28223965, 2017). "Genetically GIPR-ablated mice exhibit high fat utilization and resistance to high-fat induced obesity." (PMID 28970776, 2017). "FTO rs1421085, CDKAL1 rs2206734, TNNl3K rs1514176, GIPR rs11671664 and the GRS were associated with obesity measures at baseline and/or follow-up." (PMID 26727462, 2016). "Examples include GIPR–caffeine interaction and obesity and include LAMP3–selenium interaction and Parkinson disease." (PMID 27934696, 2016). "An observation confirmed a background of genetic deletion of gastric inhibitory polypeptide receptor (GIPR) that has previously been shown to prevent high‐fat diet‐induced obesity." (PMID 27102569, 2016). "Taken together, these observations show the importance of GIP signaling for fat storage rendering GIPR an interesting candidate for obesity." (PMID 19254363, 2009). "While preclinical in nature, this study provides clues as to how GIPR agonism and antagonism might be positioned for personalisation of obesity treatment." (PMID 41287212, 2026). "Targeting the glucose dependent insulinotropic polypeptide receptor (GIPR) is of growing interest for treating type 2 diabetes and obesity, though the optimal approach remains unclear." (PMID 41287212, 2026). "GLP-1-RA such as liraglutide, semaglutide, and the dual agonist tirzepatide, activating both the GLP1- and the gastric-inhibitory polypeptide receptor (GIP-R), have been shown to significantly reduce body weight, making them a promising therapeutic option for the treatment of obesity." (PMID 41129073, 2026). "Additionally, we observed the potential beneficial effects of CCB-targeted drugs on cSVD imaging markers and of CETP-targeted, LPL-targeted and GIPR obesity-targeted drugs on LS." (PMID 39661645, 2025). "We could not ascertain whether the activation of the GIPR or the inactivation of the GIPR can be used for the treatment of obesity." (PMID 39940910, 2025). "Although mice with adipose-specific loss of Gipr are not protected from diet-induced obesity, isoproterenol-induced lipolysis is increased in isolated GIPR deficient white adipocytes." (PMID 40024571, 2025). "The findings also demonstrate the potential beneficial effects of calcium channel blockers on cSVD imaging markers and cholesteryl ester transfer protein inhibitors, lipoprotein lipase enhancement and gastric inhibitory polypeptide receptor obesity-targeted drugs on LS." (PMID 39661645, 2025). "Co-localization analysis suggested that LPL (as a TG-lowering drug target), CETP (as an HDL-raising drug target), ABCC8 (as a glucose-lowering drug target) and GIPR (as an anti-obesity drug target) were unlikely to share a causal variant with LS." (PMID 39661645, 2025). "It should be noted that GIPR antagonism paradoxically produces additive weight loss when paired to GLP-1R agonism in preclinical studies and that this mechanism appears relevant in patients with obesity." (PMID 39963285, 2025). "Despite the clear success of agonising GIPR in the treatment of obesity, there is evidence that taking the opposite approach and antagonising GIPR activity could also be an effective treatment strategy." (PMID 40166681, 2025). "Improvement of leptin sensitivity can, however, not fully explain protection from obesity in Gipr deficient mice, since lack of GIPR decreases body weight in obese leptin deficient ob/ob mice." (PMID 40024571, 2025).
Obesity (continued). "GIPR antagonist administration suppressed body weight gain in mice with diet-induced obesity." (PMID 39940910, 2025). "Finally, for combined GIPR/GLP1R agonism, lower BMI through dual receptor activation resulted in a substantial reduction in obesity risk, with highly concordant estimates across datasets." (PMID 40931165, 2025). "In this regard, the literature, based on numerous independent and diverse observations, highlights a clear role for GIPR activation in the development of obesity, grounding the concept of GIPR antagonism as a potential approach to alleviate insulin resistance and excessive weight gain." (PMID 38861364, 2024). "In doing so, we explore the mechanisms of GIPR-based medications for treating metabolic disorders, such as type 2 diabetes and obesity, and how GIPR agonism and antagonism contribute to improvements in metabolic health outcomes, potentially through actions in adipose tissues." (PMID 38579777, 2024). "There is presently far less information available about how lipid modification of GIPR agonists alters GIPR function or interactions with membrane lipids, probably as a result of the relatively recent interest in GIPR as a therapeutic target in type 2 diabetes and obesity compared to the GLP-1R." (PMID 38614123, 2024). "The GABAergic neuron GIPR KO (GIPRΔGAT) was also protective against HFD-induced obesity." (PMID 39612941, 2024). "Interestingly, 4-hydroxybenzoic acid 2-bromobenzylidene hydrazide (4H2BH) is a small-molecular-weight compound that has been reported to inhibit both GIPR and glucagon receptor activity, with obvious dual benefits for obesity-related diabetes." (PMID 38861364, 2024). "It is not clear if antagonizing the GIP (glucose-dependent insulinotropic polypeptide) receptor (GIPR) for treatment of obesity is likely to increase the risk of fractures, or to lower bone mineral density (BMD) beyond what is expected with rapid weight loss." (PMID 38118020, 2024). "The second gene we tested was the glucose-dependent insulinotropic polypeptide receptor gene (GIPR), which may link overnutrition to obesity, insulin resistance, and type 2 diabetes." (PMID 39064800, 2024). "Finally, GIPR antagonism and global GIPR knockout in mice has also been reported to protect against obesity, and GIPR antagonists are also in the antiobesity drug development pipeline." (PMID 36719381, 2023). "Since TZT activates both GIP and GLP-1, it induces a remarkable reduction in body weight, unlike GIPR agonist, which is implicated in the development of obesity when used alone." (PMID 37208555, 2023). "A positive correlation between the GIPR level and resistance to obesity appears to exist." (PMID 37514148, 2023). "Since TZT activates both GIP and GLP-1, it induces remarkable body weight reduction, unlike GIPR agonists, which are implicated in the development of obesity when used alone." (PMID 37208555, 2023). "Studies have also reported on the beneficial role of activating, and not antagonizing, GIPR in promoting weight loss in diet-induced obesity and improved glucose homeostasis." (PMID 37443835, 2023). "Recently, the gastric inhibitory polypeptide receptor/GLP1R (GIPR/GLP1R) co-agonist, tirzepatide, became the first polyagonist approved for the treatment of T2DM; it induces a staggering 22% average weight loss in patients with obesity." (PMID 36719381, 2023). "Genetic and pharmacological inhibition of GIP and GIPR in mice protects from obesity." (PMID 38161982, 2023). "The AP and NTS mediate satiation and emerging work has shone a light on the glucose-dependent insulinotropic polypeptide receptor (GIPR) as a therapeutic target for obesity with agonism of this receptor or activation of GIPR-expressing neurons suppressing food intake." (PMID 37425814, 2023). "Furthermore, both global and CNS-specific GIPR deletion resulted in protection against obesity, suggesting that they have essential roles in induction of weight gain and adiposity." (PMID 37443835, 2023).
Obesity (continued). "Insulin-resistant states related to obesity might be associated with diminished GIP sensitivity, and GIPR expression in human adipose tissue might determine systemic insulin sensitivity." (PMID 35721732, 2022). "Thus, there are still controversies about activation / inhibition of GIPR for the treatment of obesity." (PMID 36010335, 2022). "Furthermore, a balanced unimolecular GLP‐1R and GIPR agonist reduced bodyweight, food intake, and fat mass in mice with diet‐induced obesity to a greater extent than liraglutide." (PMID 34713962, 2022). "This is highlighted by the fact that both agonists and antagonists at the GIPR could provide valuable modes of action in the treatment of T2D and obesity." (PMID 35846282, 2022). "When administered peripherally, particularly antibody-based GIPR antagonists demonstrate some potential to prevent the development of HFD-induced obesity in rodents, but GIPR antagonists show only modest, if any ability to decrease body weight once obesity is already established." (PMID 35299971, 2022). "Nonetheless, there remains great uncertainty as to whether GIPR activity should be activated or inhibited for the treatment of obesity and T2DM." (PMID 33571454, 2021). "It is currently debated whether to use GIPR agonists or -antagonists in combination with GLP-1 agonists to treat obesity and T2D, as both combinations show promising results." (PMID 34760890, 2021). "Therefore, dual agonism of GLP-1R, which exerts glycaemic control, and GIPR represents a strategy in treating obesity and T2DM." (PMID 34072172, 2021). "Genome-wide association studies (GWAS) linked GIPR and GLP1R variants with BMI and obesity." (PMID 33503878, 2021). "Early clinical results for a dual agonist peptide for both the GLP-1 and GIP receptors support a path forward for GIPR agonist approaches for treating T2D and/or obesity; however, pre-clinical data from multiple independent studies also validate a clinical strategy that employs a GIPR antagonist." (PMID 33788878, 2021). "Finally, GIP, K cell, and GIPR knockout mice are resistant to high-fat diet (HFD)-induced obesity and insulin resistance." (PMID 33788878, 2021). "Uncertainty exists as to whether the glucose-dependent insulinotropic polypeptide receptor (GIPR) should be activated or inhibited for the treatment of obesity." (PMID 33571454, 2021). "The GLP-1-agonist-GIPR-antagonist combination therapy reported in the present study was born from evidence of compromised gut-hormone function in obesity and diabetes as well as their postulated role in driving the beneficial metabolic effects following bariatric surgery." (PMID 33788878, 2021). "Long-term use of GIPR antagonists may be of exceptional benefit in lowering adiposity for treatment of obesity and its comorbidities, such as T2D." (PMID 34760890, 2021). "If same scenario applies for humans, inadequate GIPR signaling, as for R190Q and E288G, may have beneficial effects in treatment of obesity." (PMID 34760890, 2021). "Despite these findings, none of the GIPR variant carriers significantly decreased risk of obesity (data not shown)." (PMID 34760890, 2021). "Although our results together with several studies of anti-GIPR antibodies could indicate that GIPR antagonists could protect from diet-induced obesity and improve glycemic and insulinotropic effects, other studies have shown the same for GIPR agonists." (PMID 34760890, 2021). "Mice with targeted GIPR-deficiency to immune cells exhibit a deteriorated metabolic profile and significant myelopoiesis, concomitantly with impaired energy expenditure and ingWAT beiging under the setting of HFD-induced obesity." (PMID 33717200, 2021). "Nevertheless, the mechanism of GIP-stimulated adipocyte lipolysis, rather than triglyceride storage, could potentially be an anti-obesity mechanism for pharmacological doses of GIPR agonists to overcome the anti-lipolytic effects of insulin." (PMID 33020469, 2020).